ATF4 (activating transcription factor 4)
Diseases named in the same sentence as ATF4 in open-access papers (continued):
Sharing a sentence is not in itself a finding about the gene and the disease.
proliferative diabetic retinopathy (2 papers, 2025). Advanced retinopathy due to diabetes mellitus characterized by the formation of new vessels in the retina. "In proliferative diabetic retinopathy fibrovascular membranes (GSE94019), HRI elevation in normal versus diabetic endothelial (p = 0.0702) paralleled trends in ATF4 and VEGFA, implicating HRI as a conserved node in metabolic stress responses." (PMID 41010531, 2025).
prostate tumor (2 papers, 2017 to 2023). "The Catalogue of Somatic Mutations in Cancer (COSMIC) recorded a mutation in ATF4 in 16.67 % of prostate tumor tissue samples." (PMID 27587023, 2017).
rhabdomyosarcoma (2 papers, 2017 to 2025). A rare aggressive malignant mesenchymal neoplasm arising from skeletal muscle. "ATF4 also mediates the necroptosis of rhabdomyosarcoma induced by starvation, which is a potent ERS inducer." (PMID 40136668, 2025). "In addition, it was recently shown that ATF4 participates in the induction of apoptosis in response to glucose deprivation in HEK293 cells and in the necrosis of rhabdomyosarcoma cells deprived of glucose." (PMID 28242652, 2017).
small cell lung carcinoma (2 papers, 2019 to 2021). Small cell lung cancer (SCLC) is a highly aggressive malignant neoplasm, accounting for 10-15% of lung cancer cases, characterized byrapid growth, and early metastasis. "We detected ATF4 expression in human bronchial HBE cells and non-small cell lung cancer cells, including A549, H1299, and LK2 cells in vitro using western blotting and fluorescence microscopy." (PMID 33628101, 2021).
abdominal aortic aneurysm (1 paper, 2025). Enlargement and ballooning of the vessel that supplies arterial blood to the abdomen, pelvis and legs. "Pathological activation of the PERK/ATF4 ER stress response drives vascular smooth muscle cell dysfunction during abdominal aortic aneurysm formation and represents a therapeutic target." (PMID 39846252, 2025).
adenovirus infection (1 paper, 2017). "Indeed, overexpression of ATF4 by adenovirus infection leads to the induction of apoptosis of BxPC-3 cells in 2% medium as shown by the detection of the cleaved form of PARP and the significant increase of cells with a high chromatin compaction." (PMID 28460466, 2017).
adrenocortical carcinoma (1 paper, 2021). "PERK/eIF2α/ATF4 is expected to act as a potential therapeutic target for the treatment of adrenocortical carcinoma." (PMID 34567111, 2021).
age (1 paper, 2015). A temporal measurement of the time period elapsed since an identifiable point in the life cycle of an organism. "In the current study, we investigated the effects of ATF4 on one cellular process, skeletal muscle protein synthesis, which is known to be impaired in association with age-related muscle weakness and atrophy." (PMID 26338703, 2015).
aneurysmal disease (1 paper, 2025). "Our findings support this selective ER stress pathway activation during AAA development, since VSMCs from human and murine aneurysmal disease display elevated levels of TNF-α signaling as well as PERK/eIF2α/ATF4 signaling, without corresponding changes in other ER stress pathways." (PMID 39846252, 2025).
aortic aneurysm (1 paper, 2025). A ruptured aneurysm located in the wall of the proximal portion of the descending aorta proceeding from the arch of the aorta. "Additionally, studies have demonstrated that blocking PERK/ATF4 ER stress signaling protects against the progression of aortic aneurysms." (PMID 40440261, 2025).
autosomal dominant polycystic kidney disease (1 paper, 2025). Autosomal dominant form of polycystic kidney disease. "The PERK/ATF4 pathway drives amino acid biosynthesis in autosomal dominant polycystic kidney disease, and it augments antitumor activity of T cells by increasing mitophagy." (PMID 40208691, 2025).
autosomal dominant retinitis pigmentosa (1 paper, 2016). Autosomal dominant retinitis pigmentosa (RP) is an autosomally dominant inherited retinal dystrophy leading to progressive loss of the photoreceptors and retinal pigment epithelium and resulting in blindness usually after several decades. "We demonstrated a pro-death role for ATF4 overexpression during autosomal dominant retinitis pigmentosa (ADRP)." (PMID 27144303, 2016).
Blindness (1 paper, 2023). Blindness is the condition of lacking visual perception defined as a profound reduction in visual perception. "Moreover, three days after shifting these flies from 29°C back to 21°C, the number of brain-wide punctae for ATF4, XRP1 and p62 were significantly reduced indicating that blindness-induced SGs are reversible although with a significant delay." (PMID 37961457, 2023).
calcification (1 paper, 2018). Process by which organic tissue becomes hardened by the physiologic deposit of calcium salts. "We recently reported that activation of the activating transcription factor 4 (ATF4) pathway through the saturated fatty acid (SFA)-induced endoplasmic reticulum (ER) stress response plays a causative role in CKD-associated vascular calcification." (PMID 30209133, 2018).
cervical dystonia (1 paper, 2024). "Additionally, genetic and functional evidence is reported of a similar eIF2α pathway impairment in patients with sporadic cervical dystonia, owing to a rare variant in ATF4." (PMID 39512178, 2024).
cholestasis (1 paper, 2022). Impairment of the bile flow caused by obstruction within the liver, or outside the liver in the bile duct system. "Increased hepatic ER stress due to cholestasis is a major contributor to the upregulated expression of ATF4 and C/EBP-β, which mediate Sestrin2 induction." (PMID 35260799, 2022). "Immunoblot analysis of livers from Sesn2−/− mice showed marked exacerbation of ER stress upon cholestasis, as evidenced by elevated levels of phosphorylated elF2α and ATF4." (PMID 35260799, 2022). "Our results suggest that hepatic Sestrin2 expression is mediated by activating transcription factor 4 (ATF4) and CCAAT/enhancer-binding protein-β (C/EBP-β) upon cholestasis or bile acid treatment and correlates with ER stress responses." (PMID 35260799, 2022).
chronic obstructive pulmonary disease (1 paper, 2025). A chronic and progressive lung disorder characterized by the loss of elasticity of the bronchial tree and the air sacs, destruction of the air sacs wall, thickening of the bronchial wall, and mucous accumulation in the bronchial tree. "Additionally, other research has reported that PM2.5 exacerbates airway inflammation and apoptosis by activating the PERK/eIF2α/ATF4/CHOP pathway associated with ERS in chronic obstructive pulmonary disease (COPD)." (PMID 40332408, 2025).
Cirrhosis (1 paper, 2020). A chronic disorder of the liver in which liver tissue becomes scarred and is partially replaced by regenerative nodules and fibrotic tissue resulting in loss of liver function. "Both ATF4 and DDIT3 mRNA expression were significantly increased in samples of patients with HCV-related cirrhosis, where HCV viral load is fluctuating compared to the tumor tissue of patients with HCV-associated HCC where HCV viral load decrease." (PMID 32283772, 2020). "The increased expression of ATF4 and DDIT3 was specific for HCV-related cirrhosis since their expression was not induced in liver samples of patients with non-HCV end-stage liver disease as HBV-associated cirrhosis." (PMID 32283772, 2020).
encephalitis (1 paper, 2025). An acute inflammatory process affecting the brain parenchyma. "For example, the Japanese encephalitis virus induces apoptosis and encephalitis by activating the PERK pathway, whereas porcine circovirus type 2 induces ORF3-independent apoptosis by activating ER stress and the PERK-activating transcription factor 4 (ATF4)-CHOP axis." (PMID 39912666, 2025).
End Stage Liver Disease (1 paper, 2020). Final stage of a liver disease when the liver failure is irreversible and LIVER TRANSPLANTATION is needed. "To confirm our in vitro data in clinical samples, we determined the mRNA expression of transcription factors ATF4 and DDIT3 in liver biopsies from patients with end-stage liver diseases." (PMID 32283772, 2020).
familial Alzheimer disease (1 paper, 2023). A degenerative disease of the brain that causes gradual loss of memory, judgment, and the ability to function socially. "Interestingly, ATF4 and GRP75 are not induced in TMG treated familial Alzheimer’s Disease mice model." (PMID 38192280, 2023).
Friedreich ataxia (1 paper, 2021). An inherited condition that affects the nervous system and causes movement problems. "In human cells, hypoxia restored the steady-state levels of Fe-S clusters and normalized the ATF4, NRF2, and IRP2 signaling events associated with Friedreich’s ataxia (FRDA)." (PMID 34072616, 2021).
Fuchs’ dystrophy (1 paper, 2022). "In the cornea, CHOP has been implicated in the pathogenesis of Fuchs’ dystrophy and diabetic keratopathy, and ATF4 has been demonstrated in ocular surface infection and keratoconus, as well as during the lens fiber development that is required to stimulate anterior segment development." (PMID 35802384, 2022).
fungal infection (1 paper, 2018). "Neutrophils are then recruited to the cornea to fight against fungal infection.Our findings additionally indicate that ATF4 was involved in fungal keratitis both with regards to the corneal epithelium and immunocytes." (PMID 30647960, 2018).
fungal keratitis (1 paper, 2018). "Being the most commonly used mouse models for fungal keratitis research, both models showed similar ATF4 expression trends." (PMID 30647960, 2018). "Although the role of ATF4 in fungal keratitis is still not well understood, many studies have provided support to its role in inflammation." (PMID 30647960, 2018). "However, the expression of ATF4 in fungal keratitis has not been previously studied." (PMID 30647960, 2018).
helminth infections (1 paper, 2024). "Likewise, Atf4 overexpression in mouse intestinal epithelium blocks tuft cell differentiation in response to intestinal helminth infection." (PMID 39085648, 2024). "Likewise, mice overexpressing Atf4 in intestinal epithelium fail to properly respond to helminth infections due to a defective tuft cell amplification." (PMID 39085648, 2024).
hemangioma (1 paper, 2022). A benign vascular lesion characterized by the formation of capillary-sized or cavernous vascular channels. "In this sense, macrophages in hypoxic conditions express not only HIF-1α and HIF-2α, but also ATF4; more importantly, ATF4 is capable of inducing the recruitment of M2 macrophages to the tumor in a hemangioma model." (PMID 35565420, 2022).
herpesvirus infections (1 paper, 2017). "There are only limited data available with regard to the role of ATF4 in herpesvirus infections." (PMID 28202752, 2017).
homocystinuria (1 paper, 2016). An autosomal recessive inherited metabolic disorder caused by mutations in the CBS, MTHFR, MTR, and MTRR genes. "Here we show increased mRNA and protein levels of Herp, Grp78, IP3R1, pPERK, ATF4, CHOP, asparagine synthase and GADD45 in patient-derived fibroblasts suggesting ER stress and calcium perturbations in homocystinuria." (PMID 26959487, 2016). "To investigate ER stress in homocystinuria patients with remethylation defects, we have analysed the expression of genes involved in UPR (Grp78, PERK, XBP1, ATF4 and CHOP) and Ca2+ homeostasis (Herp and IP3R1) at protein or mRNA levels in controls and patients-derived fibroblasts." (PMID 26959487, 2016).
Hyperoxaluria (1 paper, 2024). Increased excretion of oxalates in the urine. "Hyperoxaluria-induced ERS also can mediate excessive autophagy via the PERK- eIF2α-ATF4 pathway to promote stone formation." (PMID 39452083, 2024).
hypospadias (1 paper, 2024). Hypospadias is the displacement of the urethral meatus on the ventrum of the penis. "In the genital tubercle of rats with hypospadias, the expressions of Akt, mTOR and S6 were reduced, while p-PERK, p-eIF2α and ATF4 proteins’ expressions increased." (PMID 39728417, 2024).
IgA nephropathy (1 paper, 2025). "ER stress characterized by increased expression of eIF2α and ATF4, molecules in the PERK pathway, was observed in MCs in response to polymeric IgA with respect to renal inflammation in IgA nephropathy." (PMID 41451198, 2025).
inclusion body myositis (1 paper, 2018). A slowly progressive degenerative inflammatory disorder of skeletal muscles characterized by late onset weakness of specific muscles and distinctive histopathological features. "ER-stress and the activation of the unfolded proteins response (UPR), as the respective cellular defence mechanism, have been described in sporadic inclusion-body myositis (sIBM), In contrast, UPR key players (ATF4, ATF6, BiP and XBP1) in muscle of GNE patients lacked any evidence of UPR induction." (PMID 29720219, 2018).
keloid (1 paper, 2021). An irregularly shaped, elevated mark on the skin caused by deposits of excessive amounts of collagen during wound healing. "In contrast, collagen type 1 alpha 2 (COL1A2) and ER stress-related genes (ATF4, CHOP, ERK, and IRE1α) were significantly upregulated in the keloid tissues." (PMID 34639105, 2021).
keratitis (1 paper, 2018). A corneal disease that is characterized by inflammation of the cornea. "Our findings indicate that as an ER stress-associated transcription factor, ATF4, is involved in the host immune response especially in the most serious stages of A. fumigatus keratitis." (PMID 30647960, 2018). "We were able to confirm that ATF4 was involved in host antifungal immune response in A. fumigatus keratitis and was dependent on TLR4, LOX-1 expression, and MAPKs pathway." (PMID 30647960, 2018). "Here, we investigated the expression of ATF4 in the host inflammatory response to Aspergillus fumigatus (A. fumigatus) keratitis." (PMID 30647960, 2018). "In conclusion, our results demonstrate ATF4 was involved in the host antifungal immune response to A. fumigatus keratitis." (PMID 30647960, 2018). "Our results clearly indicate that ATF4 was involved in the host antifungal immune response to A. fumigatus keratitis; expression was found to be dependent on TLR4, LOX-1 expression, and MAPKs pathway." (PMID 30647960, 2018). "Our results demonstrate that ATF4 was involved in the host antifungal immune response to A. fumigatus keratitis." (PMID 30647960, 2018). "Compared to the controls, ATF4 was increased in corneas from two kinds of A. fumigatus keratitis models at 3 days after infection." (PMID 30647960, 2018).
kidney cancer (1 paper, 2022). Primary or metastatic malignant neoplasm involving the kidney. "Furthermore, high levels of ISR effectors DDIT3 and ATF4 correlated with shortened patient survival in Mic60-low GBM and kidney cancer but not Mic60-high BRCA and LUAD." (PMID 35177476, 2022).
kidney stone (1 paper, 2025). "And the ER stress‐related protein expression levels of GRP78, ATF4 and CHOP, and the ratio of P‐PERK/PERK and P‐IRE1/IRE1, were significantly increased in kidney stone mouse model." (PMID 39836526, 2025).
lentivirus infection (1 paper, 2016). Virus diseases caused by the Lentivirus genus. "Cortical neurons were maintained for 10 days in vitro, with or without shCTRL lentivirus infection at DIV 5, followed by ChIP assays using anti-ATF4 or control IgG." (PMID 27841340, 2016).
limb ischemia (1 paper, 2010). A ischemia that involves the limb. "Taurine pretreatment downregulated the expression of XBP-1, ATF4, and CHOP mRNA in lung tissues following limb ischemia reperfusion (M-W test, p = 0.017, p = 0.04, and p = 0.03, respectively)." (PMID 20148646, 2010).
lipodystrophy (1 paper, 2018). A congenital or acquired disorder characterized by abnormal loss or redistribution of the adipose tissue in the body. "We observed that the expression of ATF-4, ATF-6, PERK and C/EBP Homologous Protein (CHOP), were also increased in patients with lipodystrophy compared to control subjects." (PMID 29449893, 2018).
liver cirrhosis (1 paper, 2011). "Our data correlate HF activation of the Atf4/ISR with changes in the transcription of multiple genes, including ECM regulators such as Mmp13 which was previously linked to HF anti-fibrotic effects on fibrotic potential in a liver cirrhosis model." (PMID 21974968, 2011).
lupus nephritis (1 paper, 2019). Glomerulonephritis in the context of systemic lupus erythematosus. "COX2 overexpression induced by the ATF4 ER stress pathway contributes to Lupus Nephritis-induced kidney autophagy and injury." (PMID 31024564, 2019).
lymphoid tumor (1 paper, 2021). "Our investigations show that As2O3 treatment leads to eIF2α phosphorylation, upregulation of ATF4 and TRB3 expression, and an increase of EBV Zta gene expression in lymphoid tumor cell lines as well as in naturally infected epithelial cancer cell lines." (PMID 33946406, 2021).
malignant glioma (1 paper, 2017). A grade III or grade IV glioma arising from the central nervous system. "Our data have been confirmed in independent studies: It has been demonstrated in various cancer types including malignant gliomas that ATF4 is a valid anti-cancer target." (PMID 28881638, 2017).
medullary thyroid cancer (1 paper, 2021). "They identified ATF4 as a negative regulator in medullary thyroid cancer, and a low ATF4 expression was associated with worse OS in medullary thyroid cancer patients." (PMID 34976799, 2021).
meningioma (1 paper, 2022). A generally slow growing tumor attached to the dura mater. "Moreover, our Ingenuity Pathway Analysis revealed that the transcription factors ATF3, ATF4, ATF6, and XBP1 were activated in meningioma cells exposed to DSF/Cu." (PMID 35453636, 2022).
mesothelioma (1 paper, 2022). A usually malignant and aggressive neoplasm of the mesothelium which is often associated with exposure to asbestos. "EGCG can induce endoplasmic reticulum stress in mesothelioma cells through the GRP78/ATF4/CHOP axis." (PMID 36147440, 2022).
metastasis (1 paper, 2014). The spread or migration of cancer cells from one part of the body (where they first appeared) to another. "Consequently, a subset analysis was carried out by combining ATF4 expression with lymph node metastasis status." (PMID 25078779, 2014).
muscle disorder (1 paper, 2022). "In addition, ATF4 and CHOP signaling without a clear UPR response has been observed in the context of muscle disorder." (PMID 34642769, 2022).
Mycobacterial infection (1 paper, 2021). "Mycobacterial infection can disrupt the ER to prompt ER stress, which can be induced by HIF-1α via activation of the ATF4, CHOP, and CHAC1 genes." (PMID 33535567, 2021).
myeloid leukemia (1 paper, 2020). A clonal proliferation of myeloid cells and their precursors in the bone marrow, peripheral blood, and spleen. "All together these data demonstrate that the acquisition of an ABCB1-dependent daunorubicin-resistant cellular state in myeloid leukemia cells is associated with sustained upregulation of an ISR-like transcriptional program, with the transcription factor ATF4 at its core." (PMID 31770110, 2020).
nuclear cataract (1 paper, 2025). A cataract (disease) that involves the lens nucleus. "Thus, high levels of CRYGC5bpdup transgene expression in severely affected lenses induces UPRer and UPRmt stress responses primarily through the PERK-dependent and Atf4/Atf5/Ddit3 pathways respectively, inducing autophagy and apoptosis and thence congenital nuclear cataracts." (PMID 39994382, 2025).
oesophageal cancer (1 paper, 2021). "ATF4‐Noxa is partially responsible for the cell growth inhibition of oesophageal cancer by PR‐619 treatment." (PMID 33129231, 2021).
oral squamous cell carcinomas (1 paper, 2014). "Endothelial cells from human oral squamous cell carcinomas (OSCC) were excised by laser capture microdissection (LCM) followed by analysis of UPR markers (Grp78, ATF4 and CHOP) using quantitative PCR." (PMID 24964091, 2014).